CAV1 (caveolin 1)
Diseases named in the same sentence as CAV1 in open-access papers (continued):
Sharing a sentence is not in itself a finding about the gene and the disease.
colorectal cancer (48 papers, 2011 to 2025). A primary or metastatic malignant neoplasm that affects the colon or rectum. "It has been found that low expression of miR-4728-3p in ulcerative colitis-associated colorectal cancer can influence CAV1, THBS2, and COL1A2 genes as well as focal adhesion signaling, which is related to tumor pathogenesis." (PMID 35733095, 2022). "Studies reveal that CAV-1 exerts robust anti-proliferative activity in CRC cells, and its expression is significantly downregulated in colorectal cancer patients, suggesting that CAV-1 deficiency may promote tumor progression." (PMID 41463331, 2025). "In colorectal cancer, it has been reported that stromal Cav-1 loss predicted poor survival." (PMID 28546853, 2017). "This study further showed that the expression level of stromal Cav-1 was closely associated with histological type (P = 0.022), pathologic tumor-node-metastasis stage (P = 0.047), pathologic N stage (P = 0.035), and recurrence (P = 0.000) of colorectal cancer." (PMID 28546853, 2017). "The Hsc70/caveolin-1 [CAV1]/β-catenin axis was found to participate in the progression of colorectal cancer." (PMID 40083922, 2025). "Recent research indicates that HSPA8 enhances the progression of BRAF V600E colorectal cancer by activating Wnt/β‐Catenin signalling through CMA‐mediated degradation of CAV1." (PMID 40099939, 2025). "ABCA1 overexpression stabilizes Cav1 in colorectal cancer, leading to increased invasive capacities." (PMID 39049847, 2024). "NDRG1 attenuated EMT and modulated E-cadherin expression by inhibiting caveolin-1 protein expression in colorectal cancer." (PMID 36293154, 2022). "In colorectal cancer cells, caveolin 1 (CAV1) overexpression boosts aerobic glycolysis through HMGA1-induced GLUT3 transcription." (PMID 35054987, 2022). "ABCA1 is significantly overexpressed in patients in advanced stages of colorectal cancer, and its overexpression confers proliferative advantages by regulating CAV-1 stability." (PMID 36471782, 2022). "A detailed study on colorectal cancer cells described the enhancement of aerobic glycolysis by increased CAV1 expression." (PMID 33582836, 2021). "For example, in colorectal cancer, increased CAV1 expression can promote glucose uptake via stimulating glucose transporter 3 transcription." (PMID 32082178, 2019). "On the contrary, Cav‐1 knockdown induces a senescence‐like morphological change and prevents in vitro and in vivo cellular growth in human colorectal cancer cells." (PMID 28514055, 2017). "Grb2 is expressed in colorectal cancer, and is important in its carcinogenesis, while caveolin-1 is positively regulated via the RAS/MEK/ERK pathway in this cancer." (PMID 28933766, 2017). "Collectively, these results suggest that IFITM1 is essential for the migration of colorectal cancer cells and is implicated in maintaining EMT signature through CAV1." (PMID 27852071, 2016). "In addition, HMGA1-mediated transcriptional activation of GLUT3 is responsible for oncogenic functions of caveolin 1 in colorectal cancer." (PMID 40787462, 2025). "Although the mechanistic link between CD26 inhibition and metastatic suppression was not directly explored in this study, previous reports suggest that CD26 may promote metastasis through the CAV1/MMP1 signaling axis in colorectal cancer." (PMID 40806753, 2025). "In light of previous scientific inquiries, it’s compelling to mention that many of the genes within this list of 10, specifically CAV1, DAPK1, GPX3, IGFBP6, TIMP1, GADD45B and ENO2 have been found associated intimately with colorectal cancer, as documented by several research studies." (PMID 38501104, 2024).
colorectal cancer (continued). "Through the dependency mechanism of caveolin-1 (Cav-1), isoflurane resisted the apoptosis of colorectal cancer cells, increased the proliferation and invasion of squamous cell cancer of head and neck (SCCHN), inhibited apoptosis, and promoted cancer progression and metastasis." (PMID 35966857, 2022). "To further extend this finding, we next examined plasma EVs from a cohort of colorectal cancer patients, as CAV1 has been previously associated with metastatic CRC,41, 42, 43 and hnRNPK has been detected in both EV and membrane raft proteomes of colorectal cancer." (PMID 33931969, 2021). "In colorectal cancer cells, elevated caveolin-1 increases glucose uptake and glycolysis." (PMID 32564010, 2020). "Notably, IFITM1 has recently been shown to interact with CAV-1 in colorectal cancer cells, and this interaction impacts the ability of colorectal cancer cells to migrate and invade." (PMID 26897526, 2016). "Moreover, low Cav1 expression in pre-treatment biopsies from patients with locally advanced colorectal cancer has been correlated with better rates of local control and overall survival." (PMID 26315660, 2015). "Indeed, downregulation of cav-1 in colorectal carcinoma cells decreased trafficking of CTSB to caveolae on the surface of these cells and decreased degradation of ECM proteins and cellular invasion." (PMID 21199580, 2011). "Thus, ABCA1 overexpression might lead to a stabilization of CAV‐1 protein in patients with colorectal cancer, leading to increased invasive capacities of tumour cells." (PMID 30098223, 2018). "Taken together, we observed a heterogeneity in the expression of fibroblast markers in our cohort and three proteins (αSMA, CAV1 and CD90) are suitable markers for determining fibroblast activation status to differentiate CAFs from NFs in colorectal cancer." (PMID 33802764, 2021). "It was previously shown that WNT6 expression is positively regulated by CAV1 (a scaffolding protein), UCA1 (a long noncoding RNA), and PLAGL2 (a zinc finger protein) in gastric, bladder, and colorectal cancer, respectively." (PMID 31923345, 2020). "We identified three proteins of tumorigenesis: CAV1, KPNA2, and PRMT5 being downregulated by GS treatment in colorectal cancer HCT 116 cells." (PMID 31581454, 2019). "For instance, the target complex PP1/CAV1 has already been identified in colorectal cancer cells, suggesting that CAVPENET could be directly applicable to colorectal cancer treatment." (PMID 39339236, 2024). "Furthermore, in highly metastatic cancers, another heterogeneous nuclear ribonucleoprotein (hnRNPK), driven by non-caveolin-1 (CAV1), assists the EV loading and secretion of miR-148a-3p, which favors migration of prostate and colorectal cancer cells." (PMID 36139427, 2022). "Overall, these results demonstrated that the concentration-dependent anoikis-inducing effects of SAE in HCT116 colorectal cancer cells proceeds by inducing the intrinsic apoptotic pathway through the regulation of anoikis-related signaling proteins such as EGFR, caveolin-1, Src, and Akt." (PMID 34094906, 2021). "As levels of expression of caveolin-1, uPAR, and β1-integrin were high in SUM149 cells and we have previously shown that uPA, uPAR, and β1-integrin colocalize in caveolar fractions of colorectal carcinoma cells, we isolated caveolae-enriched fractions from SUM149 cells." (PMID 22093547, 2011).
Stroke (43 papers, 2008 to 2026). Sudden impairment of blood flow to a part of the brain due to occlusion or rupture of an artery to the brain. "Cav-1 deficient mice are vulnerable to stroke as they develop larger lesions and recover less well than WT mice." (PMID 32523952, 2020). "This suggests that the attenuated morphological alterations of astrocytes after stroke in Cav-1 KO mice are linked to decreased AQP4 expression." (PMID 32523952, 2020). "The increase in BBB permeability after stroke has been linked to an early increase in transcytosis, which is caveolae and Cav-1 dependent." (PMID 32523952, 2020). "Similar to its effect in stroke models, deficiency of caveolin-1 significantly mitigated the course of EAE and reduced the albumin uptake by endothelial cells." (PMID 30523362, 2019). "In accordance with the key role of caveolin-1 in caveolae formation, caveolin-1 deficient mice exhibited reduced albumin uptake/transport to the brain parenchyma in the first hours after stroke." (PMID 30523362, 2019). "A tendency toward an increased LAA stroke risk was significant in carriers with the eNOS Glu298Asp variant in conjunction with the G14713 A and T29107A polymorphisms of the Cav-1 (aOR = 2.03, P-trend = 0.002)." (PMID 28346478, 2017). "In laboratory stroke investigations, Cav-1 levels have been associated with neuronal apoptosis, BBB disruption, infarction enlargement, and functional deterioration, yet there has been no clinical research to confirm these relationships to date." (PMID 27119011, 2016). "Activation of small GTPase RhoA, and Rho-Associated Coiled-coil Kinase (ROCK) in brain ECs via stroke promotes the association between endothelial NO Synthase (eNOS) and cav-1, leading to eNOS inhibition following its translocation to the caveolae compartments." (PMID 36139398, 2022). "As such, our findings of enhanced GAD, albumin and cav-1 immunoreactivity at 5–6 days post-stroke suggest a loss of barrier integrity at this time-point, precipitating the development of vasogenic cerebral edema, extensive midline shift and the subsequent rise in ICP seen in this model." (PMID 31338013, 2019). "Both bone marrow mesenchymal stem cell-derived extracellular vesicles (BMSC-EVs) and brain endothelial cell-derived vesicles (BEC-EVs) have been shown to significantly downregulate the elevated Cav-1 expression observed in cerebral microvessels after stroke." (PMID 41030451, 2025). "Dependent on the modulation of Cav-1, these EVs exert protective effects in stroke—including reduced endothelial permeability, attenuated cerebral infarction, and improved neurological function." (PMID 41030451, 2025). "Cav-1 and autophagy can influence the progression of stroke by disrupting tight junction proteins (TJPs)." (PMID 41030451, 2025). "In brain microvascular endothelial cells (BMECs) from stroke patients, Cav-1 mediates the endocytosis and autophagic degradation of TJPs." (PMID 41030451, 2025). "Previous studies have shown that in stroke, Cav-1 and autophagy are key factors in the disruption of these proteins." (PMID 41030451, 2025). "The box plot illustrates that in the stroke group, the expression levels of Spp1 and Cav1 were significantly elevated, whereas the expression level of Per2 was reduced." (PMID 40292254, 2025). "Firstly, post-stroke hyperglycemia enhances autophagic activity and increases the expression levels of Cav-1 and lysosomal markers (such as LAMP-2)." (PMID 41030451, 2025). "This multifaceted involvement positions the Cav-1–autophagy axis as a highly compelling therapeutic target for stroke intervention." (PMID 41030451, 2025). "miR‐199a‐5p agomir in rat stroke models manifested multiple benefits, such as improving neurological deficits, reducing infarct volume, promoting neurogenesis, inhibiting Cav‐1, and increasing VEGF and BDNF, which was reversed by the miR‐199a‐5p antagomir." (PMID 37349971, 2023).
Stroke (continued). "The serum Cav-1 level of patients with MMD intermediated between the stroke group and healthy controls and it was enhanced after the bypass surgery (681.87 ± 311.63 vs. 832.91 ± 464.41 pg/ml, p = 0.049)." (PMID 35557625, 2022). "A study of Cav-1 knockout mice showed reduced neovascularization and modified astrogliosis without proper glial scar formation around the infarct core 3 days after stroke." (PMID 36289917, 2022). "Taken together, this study demonstrated that the serum Cav-1 level of patients with MMD intermediated between the stroke group and healthy controls." (PMID 35557625, 2022). "This agrees with our previous work in ischemic stroke that showed enhanced Cav1 expression between 0.5-2.5 h after the middle cerebral artery occlusion (MCAo) model of stroke." (PMID 35832077, 2022). "In our Chinese cohort, the serum Cav-1 level of patients with MMD intermediated between the stroke group and healthy controls." (PMID 35557625, 2022). "The study highlighted caveolin-1 (cav-1)-mediated transcytosis as the initiating event in the early phase after stroke leading to subsequent TJ remodeling in the later phase." (PMID 36139398, 2022). "To further understand the molecular mechanisms of Storax regulating caveolae-mediated transcytosis after stroke, we examined Cav-1, Mfsd2a, AQP4, and PDGFR-β expressions by Western blotting." (PMID 35873558, 2022). "The divergent effects of Cav-1 in stroke point to its pleiotropic capacities, including cell growth, differentiation, cholesterol trafficking, and cellular senescence." (PMID 34501242, 2021). "We have shown that cerebral ischemia can cause Cav-1-mediated redistribution and endocytosis of Claudin-5, which causes BBB disruption in the early stages of stroke." (PMID 34531766, 2021). "Results showed circulating Cav-1 levels in stroke patients were higher than those of healthy controls, while the basic level of serum Cav-1 in patients with substantive and symptomatic hemorrhage was lower than that in other patients." (PMID 34501242, 2021). "Concomitant with the changes in AQP4 expression and coverage, reactive astrocyte morphological changes were severely diminished and brain swelling was increased in the Cav-1 KO mice after stroke." (PMID 32523952, 2020). "Here we used an integrative approach to study possible interaction between AQP4 and caveolin-1 (Cav-1) after stroke." (PMID 32523952, 2020). "Cav-1 KO mice also had a lower degree of GFAP branching after stroke in the perilesional and contralateral cortex than WTs in agreement with our earlier work." (PMID 32523952, 2020). "CST3 maintains blood-brain barrier integrity by regulating caveolin-1 expression after stroke in mice." (PMID 32733872, 2020). "Decreased GFAP staining was observed in the ipsilateral striatum of both genotypes after stroke with a larger decrease in Cav-1 KO mice than WT mice at 72 h after stroke onset." (PMID 32523952, 2020). "We recently demonstrated in Cav-1 knockout (KO) mice (JAX stock #007083) that presence of Cav-1 is associated with better survival and recovery after stroke, suggesting a protective role for endogenous Cav-1." (PMID 32523952, 2020). "Caveolin-1 and caveolin-2 can modulate the permeability of endothelium and blood-brain barrier after stroke and inhibit the release of free radicals." (PMID 33224083, 2020). "In summary, Cav-1 appears to influence AQP4 expression and distribution along vessels contributing to changes in reactive astrogliosis and brain edema observed in Cav-1 KO mice after experimental stroke." (PMID 32523952, 2020). "Following stroke, a marked increase in perivascular cav-1 immunoreactivity was observed in vehicles (E), 1×NK1 (F) and DC (L) tissue when compared to sham (D), 2×NK1 (J) and 3×NK1(K) tissue." (PMID 31333402, 2019). "Following stroke, an increase in perivascular caveolin-1 immunoreactivity was identifiable which was particularly evident at 5 and 6 days post-stroke." (PMID 31338013, 2019).
Stroke (continued). "Our IHC findings of increased cav-1 immunoreactivity at 5–6 days post-stroke corroborate this, providing a potential mechanism driving sustained barrier permeability and the evolution of cerebral edema." (PMID 31338013, 2019). "Further studies to characterize interactions between Cav-1 and lncRNAs in neuroplasticity after stroke are needed." (PMID 31673241, 2019). "The Cav-1 levels and vasogenic brain edema after ischemic insult were strongly correlated in the stroke rat models, including photothrombosis and MCAO, examined in this study." (PMID 27708218, 2016). "Cav-1 has been suggested to have a beneficial role in stroke, and Cav-1 deletion increases infarct volume after cerebral ischemia." (PMID 27708218, 2016). "Additional studies investigating the effects of Cav-1 and the cavin family on brain edema in patients with stroke are being conducted in our clinic." (PMID 27708218, 2016). "According to the data from the Nanjing Stroke Registry Programme, serum Cav‐1 level could predict the presence of cerebral microbleeds in ischaemic stroke patients, indicating that Cav‐1 might be a potential predictor of bleeding events in ischaemia." (PMID 38757755, 2024). "Although above results suggested Cav-1 plays an important role in ZO-1 and Claudin-5 redistribution and degradation post-stroke, whether Cav-1 directly or indirectly affects ZO-1 and Claudin-5 is still ambiguous, especially in permanent stroke model." (PMID 36855156, 2023). "Studies modeling stroke with transient middle cerebral artery occlusion (tMCAO) revealed that permeability occurs in a stepwise manner, with increased transcytosis through caveolin-1-mediated flux in the first 2 days, followed by increased paracellular flux thereafter." (PMID 34446062, 2021). "However, caveolae-mediated transcytosis is activated following tMCAo, and cav-1 expression increases early following stroke or brain injury, prior to TJ disassembly." (PMID 32848875, 2020). "However, the authors also observed that caveolin-1-/- mice exhibit increased stroke areas compared to those in wild-type mice." (PMID 32257548, 2020). "Similarly, AQP4 labeling in the perilesion and contralateral cortex was decreased in Cav-1 KO mice compared to WT at 6 and 72h after stroke onset (red arrows)." (PMID 32523952, 2020). "An enticing notion would be to test whether stroke disrupts the unique endothelial cell membrane lipid composition in such a way that induces cav-1 dependent transcytosis." (PMID 32848875, 2020). "Interestingly, the number of GFAP-positive processes correlated positively with perivascular AQP4 expression in WT animals after stroke but negatively in Cav-1 KO mice." (PMID 32523952, 2020). "Cav-1 is a potential therapeutic target to improve angiogenesis for the treatment of stroke." (PMID 30572925, 2018). "It is well established that cav-1 is closely related to BBB permeability in stroke." (PMID 30572925, 2018). "This hospital-based case-control study aimed to determine the genetic polymorphisms of the eNOS (Glu298Asp) and Cav-1 (G14713A and T29107A) genes in association with susceptibility risk in patients who had suffered from a large artery atherosclerotic (LAA) stroke." (PMID 28346478, 2017). "Thus, this hospital-based case-control study aimed to determine the comparative distribution of eNOS (G894T) and Cav-1 (G14713A and T29107A) polymorphisms in patients who had undergone an LAA stroke and control subjects free of neurological diseases." (PMID 28346478, 2017). "Caveolin-1 (Cav-1) plays pivotal roles in the endothelial damage following stroke." (PMID 27119011, 2016). "After stroke, deletion of astrocytic CCL2 rescued several phenotypes by Slc4a4 loss, including infarct size, BBB leakage, increased CD31 intensity, impaired tight-junctional marker expression (Claudin-5), and enhanced transcellular transport (pCav-1, Cav-1) surrounding the peri-lesion region." (PMID 38709635, 2024).